TMEM175 (transmembrane protein 175)
Diseases named in the same sentence as TMEM175 in open-access papers:
TMEM175 is named in the same sentence as 27 diseases in open-access papers, as found by Europe PMC text mining. Sharing a sentence is not in itself a finding about the gene and the disease. The quoted sentences say what the papers report.
Parkinson disease (33 papers, 2019 to 2026). A progressive degenerative disorder of the central nervous system characterized by loss of dopamine producing neurons in the substantia nigra and the presence of Lewy bodies in the substantia nigra and locus coeruleus. "The lysosomal cation channel TMEM175 plays a key role in luminal pH homeostasis and lysosome function, with aberrant activity linked to Parkinson’s disease." (PMID 41533442, 2026). "Malfunction of the lysosomal ion channel TMEM175 disrupts luminal pH homeostasis and has been linked to neurodegenerative disorders, such as Parkinson’s disease." (PMID 41533442, 2026). "TMEM175, a susceptibility gene identified for Parkinson disease by GWAS, encodes a lysosomal potassium channel under neutral pH, but recent studies suggest that TMEM175 is also an H+-activated H+ channel under a hyperacidified condition as in lysosomes." (PMID 40383150, 2025). "This connection aligns with evidence that other Parkinson’s disease–associated lysosomal transporters, including TMEM175 and ATP13A2, influence lysosomal pH and ion flux." (PMID 41332754, 2025). "In the context of Parkinson's disease, studies have revealed that a deficiency in TMEM175 leads to the excessive acidification of lysosomes consequently impairing protease activity and facilitating the aggregation of α-synuclein." (PMID 40354374, 2025). "Two of these loci, APOE and BIN1, are known as risk loci for AD15, while three—SNCA, GBA1, and TMEM175—have been found in Parkinson’s disease (PD) GWAS16." (PMID 39572598, 2024). "Remarkably, TMEM175 is a critical genetic risk locus for Parkinson’s disease, Lewy body dementia, and rapid eye movement sleep behavior disorder, showcasing its significance in maintaining the proper functions of neurons." (PMID 37238672, 2023). "Multiple genome-wide association studies (GWAS) have identified a high correlation between the p.M393T variant in TMEM175 and Parkinson’s disease." (PMID 37111358, 2023). "TMEM175 is a lysosomal ion channel, previously linked to Parkinson’s disease, and a deficiency of TMEM175 has been found to cause decreased mitochondrial respiration, altered lysosomal pH and impaired autophagy." (PMID 36747854, 2023). "A GWAS of Parkinson’s disease has identified the TMEM175/GAK/DGKQ region at chromosome 4p16.3 as a significant risk locus of this disease." (PMID 37238672, 2023). "Genome-wide association studies and functional studies in mouse models have established that TMEM175 is implicated in the pathogenesis of Parkinson’s disease, which sparks more research interests in this lysosomal channel." (PMID 37238672, 2023). "This variant, predicted to affect nonsense-mediated decay, has been associated with Parkinson and TMEM175 deficiency is linked to the increase of α-synuclein aggregation, suggesting a possible causal link." (PMID 35821807, 2022). "The TMEM175/GAK/DGKQ locus was the third strongest risk locus in a GWA study of Parkinson’s disease and has been described as a potential drug target." (PMID 34745218, 2021). "The role of TMEM175 sequence variants in the development and age of onset of Parkinson’s disease was further confirmed by several recent studies." (PMID 34638858, 2021). "TMEM175 (transmembrane protein 175) coding sequence variants are associated with increased risk of Parkinson’s disease." (PMID 34638858, 2021). "TMEM175 coding variant p.M393T is among the four strongest common genetic risk factors for Parkinson’s disease." (PMID 34638858, 2021). "Dysfunctional mitophagy resulting from TMEM175 loss-of-function mutations has been implicated in several human CNS diseases, including Alzheimer’s disease and Parkinson’s disease." (PMID 32799888, 2020). "Previous reports have established genetic and physiological evidence that TMEM175 is a potential risk factor and candidate therapeutic target for Parkinson’s disease and Alzheimer’s disease." (PMID 32799888, 2020).
Parkinson disease (continued). "The human TMEM175 channel has been linked to Parkinson disease (PD) by several genome wide association studies and is considered as a highly significant risk gene for the early onset of this neurodegenerative disease." (PMID 32267231, 2020). "TMEM175 may be linked to Parkinson's disease through several mechanisms including α‐synuclein accumulation, oxidative stress, autophagy dysfunction, and neuroinflammation." (PMID 39834146, 2025). "Dysregulation of TMEM175 may confer Parkinson's disease and Lewy body dementia risk and partly cause comorbidity." (PMID 40202048, 2025). "In summary, recent findings reveal the role of TMEM175 as a lysosomal membrane ion channel and that loss-of-function TMEM175 variants, which are associated with Parkinson’s disease, may be attractive therapeutic targets for treating this disease." (PMID 38556553, 2024). "For example, deficiency in TMEM175 could cause neuron death, motor impairment, and Parkinson's disease." (PMID 38970158, 2024). "TMEM175 coding sequence variants are associated with the development of Parkinson’s disease." (PMID 34638858, 2021). "TMEM175 is implicated in cellular proteostasis and its mutation is associated with the development of Parkinson’s disease through a yet unknown mechanism, underscoring the importance of this channel to regulation of cellular homeostasis." (PMID 32228865, 2020). "Transmembrane protein 175 (TMEM175) is a K+-selective ion channel expressed in lysosomal membranes, where it establishes a membrane potential essential for lysosomal function and its dysregulation is associated with the development of Parkinson’s Disease." (PMID 32228865, 2020). "TMEM175 has gained increasing attention over the past years because of its putative involvement in neurodegenerative diseases such as Parkinson’s and Lewy Body Dementia." (PMID 37628970, 2023). "The lysosomal cation channel TMEM175 is a Parkinson’s disease-related protein and a promising drug target." (PMID 37628970, 2023). "The association of single nucleotide polymorphisms (SNPs) in the GAK/DGKQ locus on chromosome 4 with Parkinson’s disease raised the possibility that TMEM175 gene in this region has pathophysiological significance in the neurodegenerative disorder." (PMID 34638858, 2021). "Our study indicated that the variant rs6599389 in the TMEM175 gene (effect allele A) was associated with a decrease in BMD and an increase in Parkinson’s disease risk." (PMID 32637184, 2020). "A different GWAS identified TMEM175 (transmembrane protein 175), a lysosomal K+ channel, as a potential modifier gene in patients with Parkinson disease." (PMID 31464647, 2019). "Studies have confirmed that TMEM175 is related to the pathogenesis of Parkinson's disease." (PMID 39834146, 2025). "Multiple studies indicate a potential link between TMEM175 and the onset of Parkinson’s disease." (PMID 38745204, 2024). "Future studies should be conducted to determine whether Parkinson’s disease symptoms appear in TMEM175 KO or point-mutant mice." (PMID 38556553, 2024). "It remains to be examined whether TMEM175 is present in the plasma membrane of native cells, e.g., in the dopaminergic neurons of the substantia nigra pars compacta under the pathological conditions of Parkinson’s disease." (PMID 34638858, 2021). "Notably, a series of Parkinson’s disease (PD)-related genes linked to the endomembrane system, including VPS35, LRRK2, GBA, TMEM175 and VPS13C were also identified indicating that PD proteins may act along the MAPL pathway to regulate immune signalling and cell death." (PMID 41083601, 2025). "Similarly, Tmem175 may be a potential target for Parkinson diseases." (PMID 40486922, 2025).
Lewy body dementia (6 papers, 2021 to 2025). A progressive form of dementia characterized by the presence of protein deposits called Lewy bodies in the midbrain and cerebral cortex, and loss of cholinergic and dopaminergic neurons. "Genome-wide association studies and mutation analysis have identified important SNPs of TMEM175 in many other diseases such as type 2 diabetes, breast cancer, systemic sclerosis, Lewy body dementia, and short QT syndrome." (PMID 37238672, 2023). "Interestingly, GBA1, BIN1 and TMEM175, which are associated with case–control Lewy body disease GWAS11, did not appear significant when comparing LBD-D with LBD-ND." (PMID 38978726, 2024). "Similarly, TMEM175 is a risk factor in both Lewy body diseases with and without dementia." (PMID 38978726, 2024).
dementia (2 papers, 2023 to 2024). Loss of intellectual abilities interfering with an individual's social and occupational functions. "Similarly, TMEM175 is a risk factor in both LBD with and without dementia." (PMID 37987016, 2023).
interstitial lung disease (2 papers, 2024 to 2025). A diverse group of lung diseases that affect the lung parenchyma. "A study demonstrated that resveratrol restored autophagic flux through the AKT/TMEM175 pathway to attenuate inflammation in rheumatoid arthritis‐associated interstitial lung disease." (PMID 39834146, 2025). "In summary, our findings suggest that resveratrol diminishes inflammation and fibrosis in rheumatoid arthritis-associated interstitial lung disease by reinstating autophagic lysosomal flux through the AKT/TMEM175 pathway." (PMID 38745204, 2024). "This study aimed to investigate the intrinsic mechanism by which resveratrol attenuates rheumatoid arthritis complicated with interstitial lung disease through the AKT/TMEM175 pathway." (PMID 38745204, 2024).
neuroblastoma (2 papers, 2019 to 2020). Neuroblastoma (NB) is the most common solid, extracranial childhood tumor. "Jinn and colleagues demonstrated that deficiency of TMEM175 in a neuroblastoma model resulted in lysosomal and mitochondrial dysfunction, providing functional evidence of the role of this protein in the pathogenesis of PD." (PMID 33147750, 2020). "Previously, we have demonstrated that TMEM175 KO destabilized lysosomal pH in the SH-SY5Y neuroblastoma cell line." (PMID 31261387, 2019). "Interestingly, knock-out of TMEM175 in neuroblastoma cells resulted in decreased GCase activity." (PMID 33147750, 2020).
rapid eye movement sleep behavior disorder (2 papers, 2023 to 2025). "The TMEM175 p.M393T mutation, in addition to being associated with a higher risk for PD, is also an independent risk locus for rapid eye movement sleep behavior disorder, a prodromal syndrome of alpha-synucleinopathies." (PMID 37238672, 2023). "Beyond our findings in PD and LBD, TMEM175, SNCA, and GBA were recently identified as risk genes for rapid eye movement sleep behavior disorder (RBD), an early clinical manifestation of α‐synuclein aggregation disorders associated with Lewy bodies, PD, and multiple system atrophy." (PMID 40202048, 2025).
atherosclerosis (1 paper, 2025). A disease characterized by the build-up of fatty material and calcium deposition in the arterial wall resulting in partial or complete occlusion of the arterial lumen. "Our data suggest that after TMEM175, NHE1 becomes another interesting proton efflux channel on lysosomes, but under a pathogenic condition (e.g., atherosclerosis)." (PMID 40383150, 2025).
Cerebral ischemia (1 paper, 2020). Restriction of arterial blood supply to the brain associated with insufficient oxygenation to support the metabolic requirements of the tissue. "This study aimed to understand the role of TMEM175 in lysosomal function of neurons and neuronal injury following cerebral ischemia-reperfusion (I/R)." (PMID 32799888, 2020). "In our present study, the enzymatic activities of CTSB and CTSD were also altered after OGD/R treatment, suggesting that TMEM175 deficiency exerts a negative effect on the hydrolytic function of lysosomes following cerebral ischemia with reperfusion." (PMID 32799888, 2020).
cortical atrophy (1 paper, 2023). "This evidence paves the way to an in-depth investigation of a larger cohort of patients to understand if mutations in TMEM175 may be responsible for a more severe phenotype characterized by cortical atrophy, as a result of neuroinflammation with ensuing neurodegeneration." (PMID 36609826, 2023).
Gaucher disease (1 paper, 2022). Gaucher disease (GD) is a lysosomal storage disorder encompassing three main forms (types 1, 2 and 3), a fetal form and a variant with cardiac involvement (Gaucher disease - ophthalmoplegia - cardiovascular calcification or Gaucher-like disease). "Still, a number of risk factors for LBD are linked to other neurodegenerative diseases: BIN1 (also AD), TMEM175 (Transmembrane protein 175; also PD), SNCA (also PD), APOE (also AD), and GBA (glucocerebrosidase; also PD, Gaucher’s disease)." (PMID 36421678, 2022).
Hypokalemia (1 paper, 2023). An abnormally decreased potassium concentration in the blood. "However, as a response to hypokalemia and an increased K+ release into the intracellular space, the permeability of TMEM175 for K+ may increase to keep up lysosomal K+ uptake, suggesting a physiological relevance of TMEM175-mediated K+ influx into the lysosomes." (PMID 37628970, 2023).
Lysosomal disease (1 paper, 2024). "Hence, targeting TMEM175 with small-molecule modulators could provide a therapeutic approach to treating various lysosomal diseases that are caused by defects in lysosomal acidification." (PMID 38451235, 2024). "Finally, as defective lysosomal acidification is implicated in many LSDs and neurogenerative diseases beyond PD, TMEM175 may also represent a general target for lysosomal diseases." (PMID 38451235, 2024).
synucleinopathy (1 paper, 2023). A neurodegenerative disease that is characterized by the abnormal accumulation of aggregates of alpha-synuclein protein in neurons, nerve fibers or glial cells. "Taken together, more studies are required to illustrate how mutations and variants of TMEM175 and pH changes, affect synucleinopathy etiology and progression as well as explain the dichotomous discrepancies in TMEM175 expression and PD pathology." (PMID 37964309, 2023). "Several studies investigated which alleles of TMEM175 are associated with synucleinopathies." (PMID 37964309, 2023).
Thromboembolism (1 paper, 2018). The formation of a blood clot inside a blood vessel that subsequently travels through the blood stream from the site where it formed to another location in the body, generally leading to vascular occlusion at the distant site. "Our selection ranged from targets with little biological knowledge beyond GWAS nomination (e.g., TMEM175 for Parkinson’s disease (PD)) to targets with drug candidates in early clinical trials (e.g., F11 for thromboembolism)." (PMID 30327483, 2018).
Tremor (1 paper, 2025). An unintentional, oscillating to-and-fro muscle movement about a joint axis. "SNCA and TMEM175 located in chromosome number 4 showed high frequencies and traits (e.g., age at onset, cognitive progression, motor progression, composite progression, and tremor dominant and postural instability gait difficulty, etc.)." (PMID 41026459, 2025).
neurodegenerative disease (8 papers, 2018 to 2026). A disorder of the central nervous system characterized by gradual and progressive loss of neural tissue and neurologic function. "Presented findings deepen our understanding of human TMEM175 structure–function and broaden the possibilities for developing therapeutic approaches for the treatment of TMEM175-associated neurodegenerative diseases." (PMID 41533442, 2026). "Lysosome-associated ion channels such as TRPML1, TPCN and TMEM175 have been connected to neurodegenerative diseases, such as Parkinson’s disease (PD) and Alzheimer’s disease." (PMID 34944044, 2021). "Accordingly, small molecules aimed at increasing TMEM175 function might mitigate lysosomal dysfunction in PD patients with TMEM175 mutations but also in cases of neurodegenerative disease phenotypes caused, for example, by other endolysosomal gene defects." (PMID 39902728, 2025). "In fact, a growing number of research groups are exploring the possibility of targeting key lysosomal ion channels such as TRPML1 and TMEM175 in neurodegenerative diseases." (PMID 34944044, 2021). "The combined data support a critical role of TMEM175 in fine‐tuning endolysosomal pH and provide an explanation for how changes in TMEM175 function may impact the course of neurodegenerative disease development." (PMID 39902728, 2025). "Moreover, TMEM175 may play a role in the progression of neurodegenerative diseases." (PMID 38745204, 2024). "Therefore, understanding the pharmacological relevance of TMEM175 and the development of screening assays for compounds affecting TMEM175 activity could lead to the development of novel therapeutics, potentially also for other neurodegenerative diseases." (PMID 37628970, 2023).
movement disorder (1 paper, 2017). Neurological conditions resulting in abnormal voluntary or involuntary movement, which may impact the speed, fluency, quality and ease of movement. "Other genes, such as GAK, HTT, TMEM175, FAM193A, and DGKQ, were mainly related to movement disorders (adjusted p-value = 0.0001) and basal ganglia disease (adjusted p-value = 3.73e-05)." (PMID 28118382, 2017).
TMEM175 also shares sentences with these, for which no sentence is quoted: Alzheimer disease (3 papers); neurological diseases (2); rheumatoid arthritis (2); amyotrophic lateral sclerosis (1); cognitive decline (1); Huntington disease (1); infection (1); ischemia (1); multiple system atrophy (1); Parkinson (1).